AFP (alpha fetoprotein)
Diseases named in the same sentence as AFP in open-access papers (continued):
Sharing a sentence is not in itself a finding about the gene and the disease.
gastric cancer (continued). "Hepatoid adenocarcinoma of the stomach, a rare pathological subtype of gastric cancer, is characterized by strong invasiveness, high malignancy, and poor prognosis, often accompanied by liver metastasis and elevated serum AFP levels." (PMID 40999892, 2025). "AFP-positive gastric cancer is recognized as a distinct subtype with unique biological behavior and clinical features, generally associated with poor prognosis." (PMID 40406247, 2025). "Alpha-fetoprotein-producing gastric cancer (AFPGC) is a rare, aggressive subtype with poor prognosis." (PMID 41550934, 2025). "AFP is a significant independent prognostic factor in gastric cancer, and its inclusion in a multivariate model enhances survival prediction." (PMID 40485723, 2025). "AFP-producing gastric cancer, a relatively rare malignant tumor type that accounts for 2.7%-5.4% of gastric cancers and has a high liver metastasis rate, is a high-grade cancer with a poor prognosis." (PMID 41041100, 2025). "Nonetheless, our findings still support the notion that AFP-positive gastric cancer harbors a propensity for liver metastasis, contributing to its poorer prognosis." (PMID 40485723, 2025). "In conclusion, AFP represents a significant prognostic marker in gastric cancer, and its inclusion in multivariate models enhances survival prediction." (PMID 40485723, 2025). "Gastric cancers that produce alpha-fetoprotein (AFP) are highly prone to liver and lymph node metastases, resulting in a poor prognosis." (PMID 40538847, 2025). "The study cohort comprised 766 gastric cancer patients, among whom 25 (3.3%) were identified as AFP-positive (serum AFP > 20 ng/mL)." (PMID 40485723, 2025). "When GC presents with elevated serum levels of AFP, it is referred to as alpha-fetoprotein-producing gastric carcinoma (AFPGC)." (PMID 39928247, 2025). "Clinically, GACED is categorized as an AFP-producing gastric carcinoma, which also encompasses hepatic adenocarcinoma (HAC) and yolk sac tumor-like carcinoma." (PMID 41041100, 2025). "Alpha-fetoprotein-producing gastric carcinoma (AFPGC) is a rare and aggressive subtype of gastric cancer (GC)." (PMID 39928247, 2025). "Alpha-fetoprotein producing gastric carcinoma (AFPGC) is an uncommon subtype of gastric cancer that exhibits elevated levels of AFP, constituting 1.3–5.4% of gastric cancer cases." (PMID 39902132, 2024). "The relationship between AFP expression and cisplatin efficacy in gastric cancer cells was also explored." (PMID 39135041, 2024). "Most gastric cancers with high serum AFP levels exhibit a high incidence of lymphatic invasion, venous invasion, and liver metastasis." (PMID 38355790, 2024). "In summary, these results underscore the essential role of c-Myc and c-Met upregulation in AFP-mediated cancer cell growth, influencing proliferation and cell cycle promotion in AFP-producing liver and gastric cancer cells." (PMID 39135041, 2024). "These emphasize the role of intracellular AFP in driving cancer progression and suggests its potential as a prognostic marker for liver and gastric cancer patients." (PMID 39135041, 2024). "One patient with postoperative gastric cancer was found to have a first hepatic hilum lesion on follow-up imaging, along with a significant increase in AFP levels." (PMID 38720805, 2024). "Approximately 45% of gastric cancer patients with elevated serum AFP also show increased CEA levels, classifying them as the dual-positive gastric cancer (DPGC) subgroup." (PMID 39902132, 2024). "Some serum tumor markers (especially carcinoembryonic antigen [CEA], carbohydrate antigen [CA] 72-4, CA 19-9, and alfa fetoprotein [AFP]) have been reported to be elevated in some patients with gastric cancer and have been associated with the onset, progression, and recurrence of GC 5-7." (PMID 38213731, 2024).
gastric cancer (continued). "By studying these regulatory mechanisms, we seek to enhance our understanding of AFP's contributions to tumor progression in liver and gastric cancers, providing insights into potential therapeutic strategies for AFP-producing tumors." (PMID 39135041, 2024). "A recent study has demonstrated that baseline AFP levels can predict the efficacy of immune checkpoint inhibitor therapy in advanced gastric cancer patients." (PMID 39309810, 2024). "This has led us to propose a new molecular subtyping for gastric cancer, predicated on serum AFP and CEA levels, designating cases with elevated levels of both as DPGC." (PMID 39902132, 2024). "Clinical markers such as carcinoembryonic antigen (CEA), carbohydrate antigen (CA) 199, CA724, CA125, CA242, pepsinogen, and alpha-fetoprotein are commonly used for gastric cancer screening." (PMID 38191439, 2024). "In this study, we present a case of an elderly patient who was diagnosed with AFP-producing gastric cancer (AFPGC) following an elevated AFP result during physical examination." (PMID 38812781, 2024). "The results showed that the AUC area of CEA and AFP in the diagnosis of gastric cancer was 0.669, 0.593, respectively, which was much lower than CDC45 (AUC = 0.911)." (PMID 38515458, 2024). "Further studies are needed to validate these findings and unravel the underlying mechanisms, highlighting the potential of AFP as a predictive and therapeutic target in both HCC and gastric cancer." (PMID 39135041, 2024). "In summary, patients with gastric cancer and high preoperative serum alpha-fetoprotein levels have a poor prognosis and high incidence of liver metastasis." (PMID 38355790, 2024). "It is the most common in gastric cancer and is called hepatoid carcinoma, alpha-fetoprotein (AFP)-producing carcinoma, or adenocarcinoma with enteroblastic differentiation based on the predominant microscopic features." (PMID 38672619, 2024). "Alpha-fetoprotein elevated gastric cancer (AFPGC) got growing interests for its aggressive nature and unfavorable prognosis." (PMID 38833154, 2024). "Alpha‐fetoprotein‐producing gastric cancer (AFPGC) is a rare but highly malignant subtype of gastric cancer (GC) characterized by elevated serum alpha‐fetoprotein (AFP) levels (>20 ng/mL)." (PMID 37017469, 2023). "In this study, 23 patients with AFP-GC (AFP[+]) and 18 patients with common gastric cancer (AFP[−]) were evaluated for the c-Met expression using immunohistochemical analysis." (PMID 37588998, 2023). "AFP-producing gastric cancer (AFP-GC) is a distinct histological type of gastric adenocarcinoma, characterized mainly by positive immunoreactivity to AFP and hepatoid differentiation." (PMID 37588998, 2023). "By applying single‐cell transcriptome sequencing to AFP‐producing gastric cancer (AFPGC), our study revealed novel molecular features of this rare disease." (PMID 37017469, 2023). "To ascertain the length of survival with AFPGC, we searched the literature using the terms “gastric cancer”, “AFP”,”AFPGC”, “prognosis”, and “clinicopathological” in PubMed up to 30 September 2022." (PMID 37150760, 2023). "Several AFP-producing gastric cancers have been reported to be successfully treated with combined neoadjuvant chemotherapy with epirubicin (EPI), 5-fluorouracil (5-FU), and leucovorin (LV)." (PMID 37354221, 2023). "Alpha-fetoprotein-producing gastric cancer is infrequent, accounting for at least 3% of all gastric cancers, and is generally highly malignant." (PMID 38089923, 2023). "It has been reported that the expression of miR-122-5p was significantly higher in the alpha-fetoprotein (AFP)-producing gastric cancer tissues and plasma samples." (PMID 36851037, 2023). "Some gastric adenocarcinoma patients also had elevated AFP, called AFP-producing gastric cancer (AFPGC)." (PMID 36816961, 2023). "Alpha fetoprotein (AFP) or cancer embryo antigen (CEA) can be used as characteristic markers in the early diagnosis of gastric cancer, lung cancer, breast cancer, etc.." (PMID 37298846, 2023).
gastric cancer (continued). "The patient, who was diagnosed as having alpha-fetoprotein-producing gastric cancer, died about three months later." (PMID 36046324, 2022). "Alpha-fetoprotein producing gastric carcinoma (AFPGC) is a rare type of gastric cancer with high malignancy and poor prognosis, which makes it different from other types of gastric cancer." (PMID 35886934, 2022). "Alpha-fetoprotein (AFP) is another biomarker for gastric cancer that is most commonly seen in a rare subset of AFP-producing gastric carcinomas." (PMID 36428707, 2022). "Alpha‐fetoprotein-producing gastric cancer (AFPGC) is a rare type of gastric cancer with a high rate of metastasis and poor prognosis." (PMID 36076263, 2022). "Serum levels of the tumor markers (e.g. carcinoembryonic antigen [CEA], carbohydrate antigen CA199 and CA 72-4, and alpha fetoprotein [AFP]) are elevated in some patients with gastric cancer." (PMID 35517424, 2022). "Alpha-fetoprotein-producing gastric cancer is usually identified as primary gastric cancer with a serum AFP concentration greater than 20 ng/ml or positive AFP immunohistochemical staining." (PMID 36076263, 2022). "Alpha-fetoprotein-positive gastric cancer (AFPGC) is a type of gastric cancer with a high degree of malignancy." (PMID 36387141, 2022). "This study describes a case of advanced gastric cancer in a young woman with a high blood alpha-fetoprotein (AFP) level (>54,000 ng/mL)." (PMID 36387141, 2022). "ANGPTL6 is a secreted angiogenic factor that can promote endothelial cell migration and angiogenesis in AFP-producing gastric cancer." (PMID 36421714, 2022). "The patient was definitively diagnosed as having AFP-producing gastric cancer (stage 4) with multiple lymph node metastases in the left supraclavicular fossa, lesser omentum sac, retroperitoneal, mesenteric root, and left iliac artery." (PMID 36076263, 2022). "This case demonstrates that combined capecitabine and oxaliplatin therapy can successfully treat metachronous liver metastasis from alpha-fetoprotein-producing gastric carcinoma." (PMID 36051651, 2022). "The lineage of primitive epithelial differentiated tumors that produces AFP, such as some gastric cancer, intestinal cancer and fetal adenocarcinoma of the lung." (PMID 34706681, 2021). "Four serum tumor markers including CA125, CA19‐9, CEA, and AFP were tested in 1161 of 1356 gastric cancer patients." (PMID 33934530, 2021). "As an oncofetal protein, GPC-3 is primarily present during embryonic period, but absent in normal adult tissues, whereas it’s usually up-regulated in malignant tissues such as HCC (over 80%) and AFP-producing gastric cancer (AFP-GC) (over 90%)." (PMID 34150644, 2021). "AFP is not only a biomarker for liver, testis, and ovary cancer, but is also detected in other cancer types including colorectal and gastric cancers and in xenograft tumors of neural stem cells and different cancer cell lines." (PMID 34595169, 2021). "Upregulated ANGPTL6 expression resulted in the proliferation of undifferentiated glioblastoma cells, and knockdown of ANGPLT6 in vivo significantly inhibited AFP-producing gastric cancer by regulating endothelial cell migration and tube formation." (PMID 34412629, 2021). "For patients with gastric cancer, the proportion of AFP abnormal elevation was much higher in HBsAg+patients compared with HBsAg– patients which indicated a similar mechanism of HBV‐related HCC exists in gastric carcinogenesis." (PMID 33934530, 2021). "Tumor markers (CA125, CA199, CA724, CEA and AFP) are widely used for the early diagnosis and prognostic evaluation of gastric cancer." (PMID 33937020, 2021). "Both in univariate and multivariable unconditional logistic regression model, sex, age, and AFP level were correlated with HBsAg in gastric cancer." (PMID 33934530, 2021). "For example, a review of gastric cancer research suggested the effect of AFP on the prognosis of patients with gastric cancer." (PMID 34696675, 2021).
gastric cancer (continued). "Alpha-fetoprotein producing gastric carcinoma (AFPGC) is a rare and aggressive subtype of gastric cancer." (PMID 34168152, 2021). "AFP-producing gastric carcinomas are rare, reportedly representing about 1.2% of all gastric carcinomas." (PMID 33956241, 2021). "HER2 is overexpressed in many AFP-producing gastric carcinomas and a case of fetal gut-like adenocarcinoma of the uterine cervix with amplified and overexpressed HER2 has been reported." (PMID 34977100, 2021). "α-Fetoprotein (AFP)-producing gastric carcinoma (AFPGC) is a rare and special subtype of gastric cancer (GC) associated with high liver metastasis rate and extremely poor prognosis." (PMID 34168152, 2021). "Since the suppression of miRNA-122-5p significantly reduces AFP level and the proliferation in AFP-producing gastric cancer (AFPGC), miRNA-122-5p has been regarded as a potential therapeutic target in AFPGC." (PMID 33231565, 2020). "In gastric cancer, breast cancer and lung cancer, high AFP mRNA expression was also discovered occasionally." (PMID 31897235, 2020). "Reports of cases that include an AFP-producing gastric carcinoma component are limited to 2 cases from Japan." (PMID 32972454, 2020). "The carcinomatous component included an AFP-producing gastric carcinoma and areas that showed neuroendocrine differentiation, whereas the sarcomatous component included chondrosarcomatous, leiomyosarcomatous, and rhabdomyosarcomatous regions." (PMID 32972454, 2020). "In 1970, Bourreille's group first described a case of gastric adenocarcinoma with liver metastasis, and its serum and pathological specimen were positive for AFP, which led to the term “AFP-positive gastric cancer (AFPGC)”." (PMID 31915699, 2019). "Alpha-fetoprotein-producing gastric cancer (AFP-GC) is a relatively rare disease, with a dismal prognosis." (PMID 31264022, 2019). "Alpha-fetoprotein-producing gastric cancer (AFP-GC) is a relatively rare disease, accounting for 1.3–15% cases of gastric cancer." (PMID 31264022, 2019). "The 5-year survival rates for patients with gastric cancer with AFP ≤ 20 ng/ml, 20 < AFP ≤ 300 ng/ml, and AFP > 300 ng/ml were 45.8, 17.8, and 0%, respectively." (PMID 30989433, 2019). "Previous studies have shown that HAS is the most common of the AFP-producing gastric cancers (GCs), and HAS is commonly believed to have more aggressive biobehaviour and poorer prognosis than cancers without HCC-like morphology." (PMID 30989433, 2019). "Some studies defined “AFPGC” as “gastric cancer with AFP higher than normal in the serum,” which was the definition Boureille used in the beginning." (PMID 31915699, 2019). "Consistently, human AFP-producing gastric cancers often co-express pluripotency-related proteins, such as SALL4, LIN28A, and LIN28B." (PMID 29802314, 2018). "Alpha-fetoprotein- (AFP-) producing gastric cancer (AFPGC) is characterized by a high incidence of liver and lymph node metastases and poor prognosis." (PMID 30534453, 2018). "Twenty-five gastric cancers that were diagnosed as AFP-producing gastric cancers, were examined for the expression of SALL4, LIN28A, and LIN28B by immunostaining." (PMID 29802314, 2018). "Gastric carcinoma with enteroblastic differentiation (GCED) is a rare variant of gastric carcinoma, and a part of GCED produces alpha-fetoprotein." (PMID 30228922, 2018). "Serum α-fetoprotein- (AFP-) elevated gastric cancer is a rare tumor that has a poor prognosis due to high incidence of liver metastasis." (PMID 29434637, 2017). "Alpha-fetoprotein–producing gastric cancer (AFPGC) accounts for 1.5%–7.1% of all gastric cancer cases." (PMID 28423604, 2017). "A total of 319 gastric cancer patients with liver metastasis (GCLM) whose serum AFP levels were tested before treatment were enrolled in this study." (PMID 29434637, 2017).
gastric cancer (continued). "More importantly, among the AFPGC patients who were followed for serum AFP level, serum AFP level decreased rapidly after radical operation but remained high level after palliative surgery, strongly suggesting that AFP was produced by gastric cancer cells." (PMID 28423604, 2017). "There is another case report of targeted therapy with apatinib in a patient with advanced gastric cancer and high serum level of AFP and PFS achieved five months." (PMID 29434637, 2017). "Serum AFP-elevated gastric cancer is rare, only accounts for 2.3–7.1% of all gastric cancers, but in GCLM population, our result showed that 23.2% (73/319) patients' serum AFP exceeded 20 ng/ml." (PMID 29434637, 2017). "Given this situation, the present study aims to explore the diagnostic and prognostic significance of CEA, CA19–9, AFP and CA125 for early gastric cancer." (PMID 29121872, 2017). "In most literatures, the gastric cancer patients with serum AFP elevation were found to have doughty invasiveness and poor prognosis." (PMID 29434637, 2017). "Serum AFP-elevated gastric cancer is a small subgroup of gastric carcinoma with high metastatic potential to the liver and poor prognosis." (PMID 29434637, 2017). "We examined the prognostic value of normal levels of four serum cancer markers, carcinoembryonic antigen (CEA), carbohydrate associated antigen (CA19-9), alpha-fetoprotein (AFP) and cancer antigen 125 (CA125), in gastric cancer patients." (PMID 27533455, 2016). "In this present paper, we describe a rare case of an old woman suffering from gastric cancer with an extremely high expression of serum AFP level (>10,000 ng/mL)." (PMID 27995033, 2016). "The prevalence of gastric cancer (GC) with high level of serum AFP is extremely rare, but has unique clinical features." (PMID 27631210, 2016). "AFP activates phosphatidylinositol 3-kinase(PI3K)/ protein kinase B(AKT) signalling to stimulate the expression of Ras and Src39, 40, and paclitaxel inhibited liver metastasis of AFP-producing gastric cancer cells through restraining expression of AFP41." (PMID 27255186, 2016). "We found that relatively high levels of CA19-9, AFP, and CA125 were associated with poor prognosis of gastric cancer." (PMID 27533455, 2016). "In this study, we present a case of 77-year-old woman with an extremely high expression of serum AFP level (>10,000 ng/mL) of gastric cancer." (PMID 27995033, 2016). "The present study found that relatively high levels of CA19-9, AFP, and CA125 within the normal limits were associated with a poor prognosis in gastric cancer." (PMID 27533455, 2016). "In the immunohistochemistry staining, Ki67 labeling index is significantly higher in the AFP-producing gastric cancers than in the AFP-negative gastric cancers." (PMID 27995033, 2016). "The univariate analysis showed that age, tumor size, pathological type, tumor depth, LNM, CA19-9, AFP, and CA125 were risk factors for gastric cancer." (PMID 27533455, 2016). "The prognosis of AFP-producing gastric cancer is usually poor, which is due to advanced stage, liver metastasis." (PMID 27995033, 2016). "Elevated preoperative serum CEA, CA19-9, AFP, and CA125 have been previously associated with a poor prognosis in gastric cancer." (PMID 27533455, 2016). "In most literatures, the gastric cancer patients with serum AFP elevation were given various of chemotherapy regimens but the outcome were not good enough; however, few reports were about the efficacy of apatinib." (PMID 27631210, 2016). "We herein report a unique case of apatinib treating gastric cancer with serum AFP significant increasing." (PMID 27631210, 2016). "Taken together, AFP-producing gastric cancer is a rare type of gastric cancer, with an incidence of 3% among all gastric cancers." (PMID 27995033, 2016). "Serum AFP elevated gastric cancer is a rare type of gastric cancer with doughty invasiveness and poor prognosis." (PMID 27631210, 2016).